PCAT6 (prostate cancer associated transcript 6)
Synonyms: ncRNA-a2; PCAN-R1; KDM5BAS1; onco-lncRNA-96; MGAT4EP; KDM5B-AS1
Gene: Long non-coding RNA gene on chromosome 1 (202,810,827 to 202,827,227, forward strand). Ensembl gene ENSG00000228288.
Diseases named in the same sentence as PCAT6 in open-access papers:
PCAT6 is named in the same sentence as 36 diseases in open-access papers, as found by Europe PMC text mining. Sharing a sentence is not in itself a finding about the gene and the disease. The quoted sentences say what the papers report.
lung carcinoma (19 papers, 2017 to 2024). "LncRNA PCAT6 is associated with pro-tumorigenic effects and has been implicated as having a role in lung cancer." (PMID 36787056, 2023). "Studies have shown that lncRNA PCAT6 is up-regulated in lung cancer tissues and cells and is associated with tumor progression." (PMID 33987473, 2020). "Recent studies identified that PCAT6 was significantly upregulated in lung adenocarcinoma tissues, and was positively associated with metastasis and cellular proliferation in lung cancer." (PMID 28076325, 2017). "Prostate cancer-associated ncRNA transcript 6 (PCAT6) is an oncogene in lung cancer, cervical cancer, colon cancer and gastric cancer, but its role in LSCC is still unknown." (PMID 38950346, 2024). "Moreover, quantitative real-time polymerase chain reaction (qRT-PCR) was used to examine the expression level of prostate cancer-associated transcript 6 (PCAT6) and miR-326 in lung cancer tissues and cells." (PMID 33987473, 2020). "CEACAM19 (CEA cell adhesion molecule 19), DIO3OS (DIO3 opposite strand upstream RNA), and PCAT6 (prostate cancer associated transcript 6) were verified as associated with the prognosis of different cancers, including gastric cancer, breast cancer, liver cancer, and lung cancer." (PMID 33043022, 2020). "Currently, research has demonstrated the presence of PCAT6 in the plasma of individuals with lung cancer, indicating its inherent stability." (PMID 38606479, 2024). "For example, in non-small-cell lung cancer cells, knocking down the expression of PCAT6 significantly inhibited the proliferation and migration of lung cancer cells." (PMID 37373132, 2023). "For example, high PCAT6 expression was significantly associated with TNM stage and indicated poor overall survival of patients with lung cancer." (PMID 35069911, 2022). "Functionally, they discovered that knockdown of PCAT6 significantly repressed the proliferation and invasion of lung cancer cells." (PMID 35069911, 2022). "In conclusion, LncRNA PCAT6, a vital oncogene, is first found overexpressed in lung cancer, and subsequently verified in multiple human cancers." (PMID 34885209, 2021). "Prostate cancer-associated transcript 6 (PCAT6) has been demonstrated to play a cancer-promoting role in various cancers, including gastric cancer, lung cancer, as well as cervical cancer." (PMID 34277403, 2021). "Because of high heterogeneity, we performed subgroup and sensitivity analyses, and these results revealed a significant correlation between PCAT6 overexpression and tumor metastasis in both lung cancer and osteosarcoma." (PMID 34247605, 2021). "Prostate cancer-associated transcript 6 (PCAT6), located on chromosome 1q32.1, is upregulated in various human malignancies, including lung cancer, HCC, cervical cancer, and BRCA." (PMID 34595090, 2021). "Two studies reported correlations between high PCAT6 expression and tumor size, age, degree of differentiation, and metastasis in lung cancer." (PMID 34247605, 2021). "PCAT6 was found to be highly expressed in gastric cancer, colon cancer, hepatocellular carcinoma, lung cancer, bladder cancer, ovarian cancer, breast cancer, cervical cancer, osteosarcoma, glioblastoma, and other tumors." (PMID 34327141, 2021). "Several studies have consistently demonstrated that aberrant upregulation of PCAT6 is common in lung cancer tissues and promotes the proliferation, migration, and invasion of lung cancer cells." (PMID 33634115, 2021). "Our study indicated that sevoflurane inhibited the proliferation, and invasion, but enhanced the apoptosis in lung cancer cells by regulating the lncRNA PCAT6/miR-326/Wnt5a/β-catenin axis." (PMID 33987473, 2020). "What’s more, a functional experiment suggested that the upregulation of miR-326 counteracted the impacts of PCAT6 expression on viability, proliferation, invasion, apoptosis, and activation of the Wnt/β-catenin pathway in lung cancer cells." (PMID 33987473, 2020).
lung carcinoma (continued). "In view of the important function of miR-545-3p in lung cancer, and bioinformatics analyses outlined in this work, we hypothesize that lncRNA PCAT6 may exert its physiological function by targeting miR-545-3p." (PMID 36787056, 2023). "Moreover, a new multiplex detection based on multicolor fluorescence digital PCR EV-lncRNA discovers the increased expression of exosome-derived SLC9A3-AS1 and PCAT6 in peripheral blood of lung cancer patients." (PMID 37476194, 2023). "However, no heterogeneity was observed between the included studies, the results of subgroup analysis revealed that a larger tumor volume and PCAT6 overexpression significantly correlated in lung cancer." (PMID 34247605, 2021). "After that, we assessed the level of miR-326 in lung cancer cells that were transfected with si-PCAT6 or PCAT6 vector, and we found that the level of miR-326 was markedly increased in PCAT6 down-expressing H446 and H1975 cells or decreased in PCAT6 up-expressing H446 and H1975 cells (P < 0.05)." (PMID 33987473, 2020). "Whether sevoflurane can regulate PCAT6 expression in lung cancer, and thus affect the malignant biological behavior of tumor cells has not been reported." (PMID 33987473, 2020). "We observed miR-326 expression was decreased in tumor tissues, could be upregulated by sevoflurane, and PCAT6 partly modulated lung cancer progression by sponging miR-326." (PMID 33987473, 2020). "Upregulation of PCAT6 was found in colorectal cancer, cervical cancer, and lung cancer." (PMID 33987473, 2020). "The expression of PCAT6 was increased in lung cancer tissues and cells, except for that of miR-326." (PMID 33987473, 2020). "PCAT6 may play an oncogenic role in lung cancer progression, and it negatively correlates with the overall survival of lung cancer patients." (PMID 28738804, 2017). "Our results revealed that PCAT6 was upregulated in lung cancer tissues and cells, which was induced by sevoflurane, and overexpression of PCAT6 inverted the sevoflurane’s repression on viability, proliferation, invasion, and promotion on apoptosis of human lung cancer cells in vitro." (PMID 33987473, 2020). "For example, PCAT6 targets miR-185-5p in osteosarcoma and PDAC, miR-330-5p in lung cancer and cholangiocarcinoma, and miR-143-3p in GIST and osteosarcoma." (PMID 34327141, 2021). "For example, HMGA2 is a binding partner of PCAT6 and contributes to PCAT6-mediated CRC, as well as EZH2 in CRC and lung cancer." (PMID 34327141, 2021). "We filtrated expression of lncRNAs in lung cancer cells after sevoflurane treatment, namely PCAT6, UCA1, SNHG1, CCAT2, and found that the level of PCAT6 was significantly suppressed after sevoflurane administration." (PMID 33987473, 2020). "Moreover, subgroup analysis revealed that PCAT6 overexpression did not significantly correlate with the degree of differentiation of lung cancer." (PMID 34247605, 2021). "When compared with the non-tumorigenic IMR-90, the expression of FEZF1-AS1, LIN00673 and LINC01214 was markedly higher in most lung cancer cell lines; the expression of PCAT6 and LINC01929 was strikingly lower and no clear trend was observed for the expression of NUTM2A-AS1." (PMID 32020063, 2020). "Furthermore, negative correlations between PCAT6 level and OS have been observed in patients with CRC, gastric cancer, lung cancer [33‒35], and pancreatic cancer." (PMID 38606479, 2024).
prostate carcinoma (16 papers, 2017 to 2025). A carcinoma that arises from epithelial cells of the prostate gland. "Prostate cancer-associated transcript 6 (PCAT6) is a lncRNA that was first identified to participate in the pathoetiology of prostate cancer." (PMID 36605618, 2023). "LncRNA prostate cancer-associated transcript 6 (PCAT6) was first discovered as a prostate cancer regulatory component and located on 1q32.1." (PMID 36787056, 2023). "Long non-coding RNA (lncRNA) PCAT6 is a member of the Prostate Cancer Associated Transcripts family of molecules." (PMID 34327141, 2021). "NR_046326, also named as PCAT6 (prostate cancer associated transcript 6), is located on the sense strand of chromosome 1, and is first reported highly expressed in prostate cancer." (PMID 28076325, 2017). "Additionally, lncRNA prostate cancer associated transcript 6 (PCAT6) was also found to promote bone metastasis in prostate cancer." (PMID 37069649, 2023). "At the same time, aberrant activation of the PCAT6/IGF2BP2/IGF1R axis will promote both the growth of prostate cancer and its metastasis to bone." (PMID 39771106, 2024). "PCAT6 is upregulated in cancer tissues with bone metastasis, increased PCAT6 expression predicates poor prognosis in prostate cancer patients." (PMID 37069649, 2023). "PCAT6 promotes prostate cancer bone metastasis by stabilizing IGF1R mRNA through interacting with IGF2BP2." (PMID 34185427, 2021). "In summary, the current data demonstrate that Enza-induced increase of PCAT6 expression promotes prostate cancer neuroendocrine differentiation by regulating miR-326/Hnrnpa2b1 axis." (PMID 34277403, 2021). "In prostate cancer, PCAT6 was indicated as the most upregulated lncRNA in cancer tissues and was also correlated with metastasis status." (PMID 34327141, 2021). "PCAT6 is upregulated in bone metastasis‐positive prostate cancer and PCAT6 upregulation correlates with poor prognosis in patients with prostate cancer." (PMID 34185427, 2021). "Additionally, there is potential for ST8SIA6-AS1 to impact mRNA stability or translation, similar to the mechanisms observed with lncRNA PCAT6 in prostate cancer." (PMID 39211393, 2024). "PCAT6 is actively involved in the pathogenesis of several other cancer types, including prostate cancer; it is overexpressed in almost all types of tumor tissues, and Kaplan-Meier analysis of various tumors revealed that PCAT6 overexpression is weakly correlated with patient survival." (PMID 38606479, 2024). "Furthermore, m6A methylation on lncRNA PCAT6 contributed to PCAT6 upregulation in an IGF2BP2‐dependent manner in prostate cancer." (PMID 34722298, 2021). "Furthermore, PCAT6 could enhance prostate cancer cell proliferation and colony formation in an androgen-independent manner." (PMID 34327141, 2021). "For instance, in prostate cancer, METTL3-mediated m6A modification increases the stability of the long non-coding RNA PCAT6." (PMID 40872531, 2025). "High expression of PCAT6 enhanced IGF1R mRNA stability, thus contributing to prostate cancer tumorigenesis and metastasis." (PMID 36439881, 2022).
colon cancer (11 papers, 2019 to 2024). "High PCAT6 levels were linked to the worse overall survival of colon cancer, accompanied by changing base excision repair and senescence." (PMID 36230902, 2022). "Prostate cancer-associated ncRNA transcript 6 (PCAT6) is overexpressed in colon cancer tissues and is associated with advanced clinical stages and a worse prognosis." (PMID 33246471, 2020). "PCAT6 can inhibit apoptosis and promote the progress of colon cancer by forming a complex with EZH2." (PMID 36092924, 2022). "Furthermore, PCAT6, a lncRNA, is highly expressed in colon cancer and is closely related to tumor malignancy." (PMID 34692467, 2021). "PCAT6 was reported to increase cell growth by inhibiting colon cancer cell apoptosis." (PMID 33246471, 2020). "Additionally, PCAT6 induces autophagy and improves the malignancy of colon cancer cells." (PMID 36230902, 2022). "PCAT6 activates the expression of antiapoptotic ARC and inhibits colon cancer cell apoptosis by increasing EZH2 expression." (PMID 34692467, 2021). "Analysis of 58 cases of colon cancer and 439 RNA-seq transcriptome profiles from the TCGA-colon adenocarcinoma (COAD) dataset showed that PCAT6 was significantly upregulated." (PMID 34327141, 2021). "In vitro and in vivo experiments have shown that PCAT6 inhibits cell apoptosis by promoting the enrichment of EZH2 and H3K4me3 at the ARC region, leading to an increased ARC transcriptional activity in colon cancer cells." (PMID 33246471, 2020).
non-small cell lung carcinoma (11 papers, 2019 to 2025). A group of at least three distinct histological types of lung cancer, including non-small cell squamous cell carcinoma, adenocarcinoma, and large cell carcinoma. "For example, lncRNA prostate cancer associated transcript 6 promotes non-small-cell lung cancer cell growth, migration and invasion by repressing the expression of large tumor suppressor kinase 2 via binding with the epigenetic repressor EZH2." (PMID 35291911, 2022). "Another non-small cell lung cancer study identified the long non-coding RNA (lncRNA) PCAT6 (prostate cancer-associated transcript 6) as a promoter of migration and invasion though regulation of miR-330-5p." (PMID 31391080, 2019). "Specifically, the lncRNA PCAT6 regulates the microRNA (miR)-326/ Krüppel-like factor 1(KLF1) axis in non-small cell lung cancer (NSCLC) cells." (PMID 40722682, 2025). "For example, knockdown of the exosomal lncRNA PCAT6 in non-small cell lung cancer (NSCLC) using siRNA can suppress M2 polarization via the miR-326/KLF1 axis and extend tumor growth." (PMID 39925739, 2025). "PCAT6, lied on chromosome 1q32.1, functions as a tumor activator in multiple types of cancers like non-small-cell lung cancer, osteosarcoma, gastric cancer, and hepatocellular carcinoma." (PMID 34277403, 2021). "Numerous studies have shown that PCAT6 also plays an important role in tumor proliferation and invasion, such as in non-small cell lung cancer, breast cancer, cervical cancer, and liver cancer." (PMID 34692467, 2021). "For instance, the lncRNA PCAT6 was shown to inhibit non-small cell lung cancer cell proliferation, apoptosis, and metastasis through epigenetic mechanisms." (PMID 32025371, 2020).
gastric cancer (10 papers, 2020 to 2024). A primary or metastatic malignant neoplasm involving the stomach. "PCAT6 has also been reported to be overexpressed in gastric cancer tissues and to promote the development of gastric cancer." (PMID 33634115, 2021). "PCAT6 has been reported to be upregulated in many types of cancers including bladder cancer, breast cancer, cervical cancer, CRC, gastrointestinal stromal tumor, gastric cancer and other cancers." (PMID 38606479, 2024).
bladder cancer (9 papers, 2021 to 2024). "As no heterogeneity was observed between the included studies, therefore, it can be concluded that PCAT6 overexpression and a larger tumor volume were associated in lung, colorectal, and bladder cancers." (PMID 34247605, 2021). "Conversely, individuals with elevated PCAT6 level in bladder cancer, osteosarcoma, and ovarian cancer patients exhibited shorter OS and progression-free survival (PFS) time." (PMID 38606479, 2024). "For instance, as a ‘sponge’ for miR-513a-5p, lncRNA PCAT6 promotes the development of bladder cancer." (PMID 38950346, 2024). "Recently, PCAT6 expression was found to be upregulated in bladder cancer tissues and cell lines, and high expression of PCAT6 was associated with reduced overall survival." (PMID 36605618, 2023). "For example, the expression of lncRNAs such as TUC338 and PVT1 can be used as biomarkers for early diagnosis of bladder cancer, while the expression of PCAT6, NRON, GAS6-AS2, SNHG3, lncRNA TP73-AS1, and LINC00641 can predict poor prognosis of bladder cancer." (PMID 37592177, 2023). "A study of bladder cancer showed that overexpression of PCAT6 can promote the progression of bladder cancer by targeting miR-513a-5p." (PMID 36092924, 2022). "In bladder cancer, METTL3 upregulates PCAT6 expression and increases IGF1R RNA stability by forming the PCAT6/IGF2BP2/IGF1R complex, which activates the NF-KB and PI3K/AKT signaling pathways." (PMID 37996892, 2023).
cervical cancer (9 papers, 2020 to 2024). A primary or metastatic malignant neoplasm involving the cervix. "LncRNA prostate cancer-associated transcript 6 (PCAT6), which was first identified in keratinocytes, indirectly activates the Wnt/β-catenin pathway by interacting with KLHL12 in cervical cancer cells." (PMID 34247605, 2021). "PCAT6 also enhances chemoresistance to cisplatin in cervical cancer by sponging miR-543 and activating ZEB1 expression." (PMID 34277403, 2021). "Regarding the correlation between PCAT6 overexpression and tumor size, PCAT6 overexpression and a larger tumor volume significantly correlated (after excluding cervical cancer and osteosarcoma)." (PMID 34247605, 2021). "Moreover, PCAT6 can facilitate the proliferation and metastasis of cervical cancer cells but suppress apoptosis via the PCAT6/miR-543/ZEB1 axis." (PMID 33634115, 2021). "Previous univariate/multivariate Cox regression analysis confirmed that PCAT6 expression influences the prognosis of patients with CRC, cervical cancer, liver cancer, and osteosarcoma." (PMID 38606479, 2024).
breast carcinoma (8 papers, 2020 to 2025). "Herein, it is revealed that the enhanced hypoxic long no‐ncoding RNA (lncRNA prostate cancer associated transcript 6 (PCAT6) in breast cancer (BC) promotes the nuclear export of m6A‐modified mRNAs, bolstering breast cancer stem cells (BCSCs) stemness and doxorubicin resistance." (PMID 38626369, 2024). "In particular, enhanced PCAT6 expression in chemotherapy‐resistant breast cancers further supported that PCAT6 is a tumor‐promoting lncRNA." (PMID 38626369, 2024). "In breast cancer, PCAT6 acts as a sponge for miR-4723-5p to regulate VEGFR2, and also participates in the VEGFR/AKT/mTOR signaling pathway to accelerate angiogenesis." (PMID 34327141, 2021).
cholangiocarcinoma (8 papers, 2020 to 2024). A carcinoma that arises from the intrahepatic biliary tree (intrahepatic cholangiocarcinoma) or from the junction, or adjacent to the junction, of the right and left hepatic ducts (hilar cholangiocarcinoma). "For example, in cholangiocarcinoma, the lncRNA prostate cancer-associated transcript 6 (PCAT6) mediates M2 polarization through a ceRNA network in which lncRNA PCAT6 suppresses the expression of miR-326 and promotes the expression of RhoA, a target gene of miR-326." (PMID 36263199, 2022). "It was also found that PCAT6 induced M2 polarization of macrophages in cholangiocarcinoma via competitive binding to miR-326, and modulated the RHOA signaling pathway." (PMID 34771549, 2021). "In cholangiocarcinoma, PCAT6 directly targeted and reduced miR-330-5p levels, resulting in induced cell proliferation and invasion." (PMID 34327141, 2021). "Thus, PCAT6 could be a potential immunotherapy target for cholangiocarcinoma treatment." (PMID 36263199, 2022). "Thus, PCAT6 may be a potential target of immunotherapy in cholangiocarcinoma treatment." (PMID 34771549, 2021). "For instance, LncRNA PCAT6 is upregulated in cholangiocarcinoma tissues compared to normal tissues, and its expression is correlated with TNM staging." (PMID 38637832, 2024).